MAPK3 (mitogen-activated protein kinase 3)
Diseases named in the same sentence as MAPK3 in open-access papers (continued):
Sharing a sentence is not in itself a finding about the gene and the disease.
acute pancreatitis (5 papers, 2021 to 2024). An acute inflammatory process that leads to necrosis of the pancreatic parenchyma. "Using PPI and molecular docking, we found that MAPK3 (ERK1) is an effective target for the treatment of acute pancreatitis." (PMID 39764471, 2024).
silicosis (5 papers, 2013 to 2023). Silicosis is a respiratory disease caused by breathing in (inhaling) silica dust. "Next, it was confirmed that gene expression of BMP4 and MAPK3 were higher in PBMCs from patients with silicosis." (PMID 34517882, 2021). "In the present study, MAPK3 (ERK1) was significantly increased in PBMCs from patients with silicosis compared to that in the control group." (PMID 34517882, 2021). "MAPK3 (ERK1) levels are dramatically elevated in the peripheral blood mononuclear cells of patients with silicosis, and crystalline silica may accelerate the release of ROS." (PMID 37381044, 2023). "Dysregulation of MAPK3 plays a significant role in the pathological processes of silicosis." (PMID 34517882, 2021). "Crystal compounds in silicosis activate ROS, which activate the inflammasome through MAPK3." (PMID 34517882, 2021). "ROS further activate the inflammasome through MAPK3 and phosphorylate Ser276 of p65 NF-κB and Ser641 and Ser643 of HIF-1α, to promote the development of silicosis." (PMID 37381044, 2023). "The results indicated that the expression of SMAD2, MAPK3, THBS1, ITGB3, and BMP4 was increased, while the expression of SMAD3 and CD44 was significantly low expression in PBMCs from patients with silicosis, indicating consistent results with the RNA-Seq data." (PMID 34517882, 2021).
ZIKV infection (5 papers, 2017 to 2026). "The inflammatory profile is partially different following ZIKV infection, which is mainly characterized by less inflammatory response and by the specific induction of several MAPK genes (MAP2K1, MAP2K3, MAP3K7, MAPK1, MAPK3)." (PMID 28873445, 2017).
cardiac arrest (4 papers, 2017 to 2024). Cessation of breathing and/or cardiac function. "We speculated that the ferroptosis-related gene MAPK3 might be associated with neurological prognosis after cardiac arrest." (PMID 38885209, 2024). "In summary, the MAPK3 ferroptosis-related gene could be used as a biomarker to predict the neurological outcome after cardiac arrest." (PMID 38885209, 2024). "Next, to validate the expression of AKT1, BCL2, and MAPK3 in the large cohort of cardiac arrest patients, we recapitulated gene expression levels of AKT1, BCL2, and MAPK3 in the datasets available from the NCBI, GEO database (GSE29540)." (PMID 28147324, 2017).
chordoma (4 papers, 2011 to 2025). Chordomas are rare malignant tumors arising from embryonic remnants of the notochord in axial skeleton. "In addition to the well‐known chordoma biomarkers (LGALS3 and TBXT), the heatmap also revealed IGKV2, IL13RA2, RAB3B, and MAPK3 highly expressed in chordoma." (PMID 40135815, 2025).
choriocarcinoma (4 papers, 2015 to 2024). An aggressive malignant tumor arising from trophoblastic cells. "Another study demonstrated a time-dependent elevation of p-Mapk3 protein levels in human chorionic carcinoma cell line JEG-3 treated with 10 μM ATR, resulting in disrupted endocrine development." (PMID 39231689, 2024).
leiomyoma (4 papers, 2019 to 2023). A well-circumscribed benign smooth muscle neoplasm characterized by the presence of spindle cells with cigar-shaped nuclei, interlacing fascicles, and a whorled pattern. "The reactive oxygen species (ROS) is able to induce the proliferation of leiomyoma smooth muscle cells and it is also necessary for triggering the MAPK1/MAPK3 signaling pathway, which contributes to leiomyoma smooth muscle cell proliferation." (PMID 35800452, 2022).
mental disorder (4 papers, 2023 to 2025). A disease that has its basis in the disruption of mental process. "A transcriptome-wide association study (TWAS) using data from a large SCHZ genome-wide association study (GWAS) identified a genetic correlation between Mapk3 expression and this mental disorder." (PMID 40299488, 2025). "Nevertheless, as BDNF is associated with several mental disorders, MAPK3 differential expression may also not be restricted to social anxiety." (PMID 37181876, 2023).
muscular dystrophy (4 papers, 2013 to 2025). Muscular dystrophy (MD) refers to a group of more than 30 genetic diseases characterized by progressive weakness and degeneration of the skeletal muscles that control movement. "Since the depletion of SCs was achieved through a complicated genetic background (Sgcd−/−; Mapk3−/−; Mapk1f/f−Pax7Cre−ER), a simple depletion of SCs using mAbs is thought to be essential to obtain a proof of concept for the therapy of muscular dystrophy." (PMID 40688506, 2025).
Salmonella Infections (4 papers, 2018 to 2022). Infections with bacteria of the genus SALMONELLA. "Other genes known to be associated with Salmonella infection were also upregulated, including a variety of chemokines, RELA, ARPC4 and MAPK3." (PMID 35711662, 2022).
Cervical Squamous Cancer (3 papers, 2015 to 2019). "Moreover, it was found that the phosphorylation of MAPK1/MAPK3 was correlated with tumor growth in OSCC, the methylation of ESR1 promoter was associated with squamous cell cervical cancer, and the activation of FYN kinase was related to OSCC." (PMID 26064958, 2015).
hearing loss (3 papers, 2018 to 2024). "A comprehensive network and pathway analysis indicated that the MAPK3/MAPK1 MAP kinase serves as one of the crucial nodal molecules in regulating human genetic deafness, highlighting the close association between MAPK signaling pathway and hearing loss." (PMID 29340520, 2018).
hepatitis B (3 papers, 2015 to 2024). "Our research proposed that MTOR, MAPK3, and EGFR are directly involved in hepatitis B pathways." (PMID 35745580, 2022).
Infertility (3 papers, 2016 to 2021).
Intellectual disability (3 papers, 2021 to 2023). "MAPK3 is located within the chromosome 16p11.2 band that is associated with 16p11.2 deletion syndrome, characterized by intellectual disability and developmental delay." (PMID 35893067, 2022).
myopia (3 papers, 2023 to 2025). "The 6 important intersectional targets of DZP for myopia treatment were STAT3, PIK3CA, PIK3R1, MAPK1, MAPK3, and HSP90AA1." (PMID 37747014, 2023).
rectal cancer (3 papers, 2010 to 2021). A primary or metastatic malignant neoplasm that affects the rectum. "Among 718 colon and rectal cancers, phosphorylated AMPK (p-AMPK) and p-MAPK3/1 expression was detected in 409 and 202 tumours, respectively, by immunohistochemistry." (PMID 20808308, 2010).
visceral leishmaniasis (3 papers, 2019 to 2023). A severe form of leishmaniasis characterized by irregular bouts of fever, substantial weight loss, swelling of the spleen and liver, and anemia (which may be serious). "The recombinant MAPK3 used in serodiagnosis showed better specificity and efficacy in the immunodiagnosis of visceral leishmaniasis." (PMID 31700105, 2019). "Therefore, from the literature evidence, the authors conceived the idea of characterizing MAPK3 of L. donovani and use it as a drug target against visceral leishmaniasis." (PMID 31700105, 2019).
alopecia (2 papers, 2018 to 2024). Hair loss usually from the scalp. "Contrary to the alopecia-inducing effects of the earlier hub genes, STAT3, HIF1A, and MAPK3 are reported to counteract hair loss." (PMID 39056691, 2024).
ameloblastoma (2 papers, 2018 to 2022). The most common odontogenic tumor, arising from the epithelial component of the embryonic tooth and usually affecting the molar-ramus region of the mandible or maxilla. "According to the present results, MAPK3 was underexpressed in ameloblastoma samples compared to the corresponding healthy controls (FC = 0.33; P value = 0.005)." (PMID 36160115, 2022). "Besides, “MAPK1/MAPK3 signaling” (R-HSA-5684996), “MAPK family signaling cascades” (R-HSA-5683057), “MAPK6/MAPK4 signaling” (R-HSA-5687128), and “MAPK cascade” (GO:0000165) were also dysregulated in ameloblastoma." (PMID 36160115, 2022).
arteriovenous malformations of the brain (2 papers, 2020 to 2025). "Variants like rs55859133 may influence the expression or function of MAPK3, potentially affecting pathways related to angiogenesis and vascular health (there is a mutational spectrum of syndromic genes involved in sporadic brain arteriovenous malformation)." (PMID 40564170, 2025).
delirium (2 papers, 2022 to 2023). A disorder characterized by confusion; inattentiveness; disorientation; illusions; hallucinations; agitation; and in some instances autonomic nervous system overactivity. "The reported MAPK signaling pathway-related hub proteins, namely MAPK1, MAPK3 and MAPK14, might be involved in delirium-associated neurological disorders/activities which demand deeper investigation." (PMID 37993790, 2023). "The MAPK signaling pathways might be crucial for delirium pathophysiology since the key delirium-associated hub proteins MAPK1, MAPK3, and MAPK14 were found to be associated with it." (PMID 37993790, 2023).
insomnia (2 papers, 2021 to 2024). A sleep disorder characterized by difficulty in falling asleep and/or remaining asleep.
lung neoplasm (2 papers, 2014 to 2020). A benign or malignant, primary or metastatic neoplasm involving the lungs. "For instance, SF(Pkinase, Death) contains seven members (MAP3K8, MAPK3, MAPK14, MAPK1, AKT1, CHEK2, and DAPK1) that are related to lung neoplasms." (PMID 31937869, 2020).
prostate adenocarcinoma (2 papers, 2017 to 2025). "QRT‐PCR analysis showed significantly lower expression of the genes: MAPK3 encoding ERK1 and MAPK1 encoding ERK2, p38, β‐catenin and E‐cadherin in prostate adenocarcinoma compared to BPH tissues." (PMID 40839490, 2025).
somatotropinoma (2 papers, 2015 to 2018). "Rat somatotropinoma-derived GH3 cells secrete SOD1, which, via activation of a muscarinic M1 receptor, reduces the activity of the MAPK1 signaling pathway, by inhibiting MAPK3 phosphorylation, reducing cell proliferation." (PMID 29507682, 2018).
tongue cancer (2 papers, 2019 to 2022). A malignant neoplasm affecting the tongue. "Our results suggest MAPK1, AKT1, and MAPK3 as potential drug targets in NACT resistant tongue cancer patients." (PMID 36393868, 2022).
chloroma (1 paper, 2021). "The backward elimination procedure identified RUNX1T1, MAPK3, PIK3CG, TCF7L1, GRB2, and MTOR as the empirical drivers of the association with chloroma." (PMID 33882829, 2021).
coagulopathy (1 paper, 2025). "The involvement of JUN, FOXO1, and MAPK3 in complement and coagulation cascades suggests their potential role in immune-mediated inflammation and coagulopathy, which are frequently observed in HIV-infected individuals." (PMID 40574839, 2025).
lumbar disc herniation (1 paper, 2025). "Furthermore, this study suggests that the 3 bioactive components of Guizhi Fuzi decoction (naringenin, β-sitosterol, and stigmasterol) may exert their therapeutic effects on lumbar disc herniation by specifically targeting MAPK3." (PMID 40128047, 2025).
Macrocephaly (1 paper, 2022). Occipitofrontal (head) circumference greater than 97th centile compared to appropriate, age matched, sex-matched normal standards. "The KCTD13 gene is a key driver of neuronal proliferation in zebrafish and mice and a major driver of the 16p11.2 microdeletion syndrome macrocephaly, and MAPK3 and MVP genes in the deletion region may act as modifier genes to enhance the expression of KCTD13 gene." (PMID 36553582, 2022).
male infertility (1 paper, 2022). The inability of the male to effect fertilization of an ovum after a specified period of unprotected intercourse. "Mitogen-activated protein kinases (MAPKs) play a crucial role in the regulation of spermatogenesis and spermatozoa functions, and MAPK1 and MAPK3 were also recognized as key target genes of SJC for male infertility due to their higher BC." (PMID 36401273, 2022).
opioid use disorder (1 paper, 2022). A substance-related disorder that involves the recurring use of opioids despite negative consequences. "Levels of phosphor-Mapk3 (Erk1) were significantly downregulated in the prefrontal cortex of postmortem tissue from patients with opioid use disorder, although expression of Mapk3 (Erk1) has also been reported to be upregulated in the locus coeruleus and striatum of rats treated with morphine." (PMID 35163373, 2022).
pancreatic disease (1 paper, 2021). "A new finding of the present study is that affected patients from one FPC family can carry identical germline variants in up to three different genes, e.g., DAB1, POLQ and FGFBP3 in family 25-9-44 or MAPK3 and ACAD9 in family 25-4-46, which segregate with pancreatic disease." (PMID 34357098, 2021).
parasitic infection (1 paper, 2024). "Therefore, targeting MAPK3 may facilitate the discovery of newer small-molecule inhibitors as candidate drugs for parasitic infection treatment." (PMID 39625960, 2024).
pharyngitis (1 paper, 2020). Inflammation of the throat most often caused by viral and bacterial infections. "DC, CC, and BC analysis indicated that ALB (serum albumin), PPARγ (peroxisome proliferator-activated receptor gamma), MAPK3 (mitogen-activated protein kinase 3), EGF (epidermal growth factor), and PTGS2 (prostaglandin G/H synthase 2) are closely related to pharyngitis." (PMID 33101439, 2020).
SARS-CoV infections (1 paper, 2022). "It was found that 45.87% of the associated genes (CASP3, CASP9, MAPK1, MAPK3, XIAP) contributed to cytochrome C-mediated apoptotic response and 3.67% of the associated genes (BECN1, FXYD2, GSK3B, HSP90AA1, ITGB1, MAP1LC3B) contributed to SARS-CoV infections." (PMID 36164436, 2022).
Tinnitus (1 paper, 2022). Tinnitus is an auditory perception that can be described as the experience of sound, in the ear or in the head, in the absence of external acoustic stimulation. "The core components of Liuwei Dihuang Pill in the treatment of tinnitus including quercetin, stigmasterol, kaempferol, β-sitosterol, tetrahydroalstonine, which may act on core targets such as STAT3, transcription factor AP-1 (JUN), tumor necrosis factor (TNF), interleukin-6 and MAPK3." (PMID 36401375, 2022).
transitional carcinoma (1 paper, 2020). "MAPK-3 analysis showed a sensitivity of 88, 87, 72, and 88% and specificity of 94, 100, 56, and 99% for diagnosis of BC, BBC, transitional carcinoma, and high grade malignancy respectively." (PMID 33139749, 2020).
vasculitis (1 paper, 2022). "Based on PPI analysis, the overlapped genes with higher degrees in the hub gene network included MAPK1, MAPK3, VEGFA, TNF, and AKT1, implying that they were involved in the process of HXTLF treatment against vasculitis." (PMID 36034958, 2022).